IL6 (interleukin 6)
Diseases named in the same sentence as IL6 in open-access papers (continued):
Sharing a sentence is not in itself a finding about the gene and the disease.
ischemia (continued). "Little information is available about the cell types within the heart that preferentially produce IL-6 or the mechanisms by which ischemia regulates IL-6 formation." (PMID 36943408, 2023). "Radiation-induced thrombosis and ischemia can also cause an increase in the production of pro-inflammatory and inflammatory cytokines and chemokines, such as TNF-α, IL-1, and IL-6, which attract inflammatory cells to the wounded jaw." (PMID 37081475, 2023). "After ischemia, NF-κB regulates the upregulation of inflammatory mediators, including IL-1, IL-6, IL-8, iNOS, ICAM 1, VCAM and E-selectin, and then leads to neutrophil infiltration and adhesion molecule induction." (PMID 36793730, 2023). "Administration of Captopril, Losartan, or their combination resulted in a significant (p < 0.01) decrease in TNF-α, IL-1β, and IL-6 levels which was increased at the beginning by ischemia compared to untreated controls." (PMID 37259385, 2023). "Recently, compelling evidence has delineated the role of DCs in hepatic I/R injury and several results support that DCs modulate levels of IL-6 and IL-10 in liver submitted to ischemia injury." (PMID 37593740, 2023). "Another finding of interest of SAMet treatment in our model is related to the effect on IL-6, which is reduced at the level of the portal and cava veins after ischemia and subsequent reperfusion." (PMID 37627534, 2023). "Microglia, known as the brain tissue macrophages, play a pivotal role by producing IL‐6 in response to ischemia." (PMID 37143406, 2023). "It is also an acute phase reactant, increased by inflammatory mediators, such as interleukin-6, known to rise after ischemia." (PMID 37267281, 2023). "Following ischemia, M1 are rapidly activated and release a variety of inflammatory mediators, such as IL-1 β, IL6, and TNF." (PMID 36598916, 2023). "The release of inflammatory factors (e.g., TNF-α, IL-6, and IL-1β) after ischemia-induced macrophage activation is responsible for IR damage and for exacerbating liver microcirculation disorders." (PMID 35966821, 2022). "The anti-inflammatory effects of Tat-CHIP were assessed in the hippocampus 6 h after ischemia induction by measuring pro-inflammatory cytokine levels, such as IL-1β, IL-6, and TNF-α." (PMID 36450819, 2022). "Caspase 3, IL-1 β, and IL-6 expressions were severely increased in ischemia and I/R groups, while the severity of I+ASX50 and I/R+ASX100 immunoreactivity was decreased." (PMID 35655595, 2022). "In the current study, AKI did result in significant increase in levels of TNF-α and IL-6 in the blood, kidney and hypothalamus at 24 h after ischemia." (PMID 35530034, 2022). "Another study demonstrated that cross-linking TIM-1 and TIM-4 in macrophages results in TNF-α/IL-6 secretion and contributes to ischemia reperfusion-induced liver damage." (PMID 35990621, 2022). "Multiple microglia-related genes such as Cxcl10, Tlr7, Cd86, Tnfrsf1a, Nfkbia, Tgfb1, Ccl2 and Il-6, were upregulated with prolonged ischemia." (PMID 35154109, 2022). "After ischemia, plasma levels of proinflammatory cytokines, such as TNF-α, IL-1, and IL-6, increase significantly and cause exacerbation of tissue damage." (PMID 38812980, 2022). "Hydrogen gas inhalation has been proven to decrease the levels of inflammatory cytokines, including TNF-α, IL-1β, and IL-6, in ischemia/reperfusion injury or the retina, liver, and brain." (PMID 34769482, 2021). "During ischemia, cytokines, such as IL-1β, IL-6 and TNF-α are produced by a variety of activated cell types, including microglia and neurons (Huang, Upadhyay & Tamargo, 2006)." (PMID 34123580, 2021). "Astrocytes have been found to produce inflammatory cytokines, including IL-6 and TNFα, following traumatic injury and ischemia." (PMID 34071762, 2021).
ischemia (continued). "Intriguingly, the naturally occurring selective antagonist of IL-1 receptor antagonist IL-1Ra blocks upregulation of IL-6 and has been shown to protect against experimentally induced ischemia, traumatic brain injury and perinatal hypoxia in rodent models." (PMID 33923626, 2021). "TNF-α, IL-1β, and IL-6 are the major pro-inflammatory cytokines that aggravate the inflammatory response after ischemia injury." (PMID 34238326, 2021). "Remote IPOC also increased the expression of p‐ERK in the ipsilateral hemisphere of the ischemia and attenuated the level of IL‐6 in peripheral blood." (PMID 34559467, 2021). "It has been suggested that the myocardium produces IL-6 during phases of compromised myocardial function as a result of ischemia and reperfusion injuries." (PMID 33771227, 2021). "AP39 also exerted prominent anti-inflammatory activity in reducing the release of Il-1β, Il-6 and TNFα in brain areas particularly affected by ischemia." (PMID 34360581, 2021). "This is in agreement with a study of cerebral ischemia in neonates, where early response to ischemia led to an increase of IL-6." (PMID 33918875, 2021). "Because, we only observed a significant increase in Il6 mRNA levels in the IR + UNx group at fourth-month post-ischemia, the IL6 protein levels were only evaluated in the Sham and IR + UNx groups in this specific time of the study." (PMID 33888767, 2021). "In a previous report after generalized ischemia, we indeed also observed that IL-6 was activated very early, whereas IL-1β or tumor necrosis factor-alpha were not." (PMID 33806919, 2021). "In the Tat peptide- and Control-SH3GL2-treated groups, TNF-α, IL-1β, and IL-6 levels were significantly increased in the hippocampus 6 h after ischemia compared to those in the control group." (PMID 33572372, 2021). "In summary, the pretreatment with GPE-R significantly promotes the survival of neurons in the hippocampal CA1 region after ischemia/reperfusion by reducing reactive microglia and pro-inflammatory cytokines such as IL-6, IL-1β, and TNF-α." (PMID 33435613, 2021). "The IL-6 immunostained positive cells had demonstrated a significant decrease after 30 minutes of ischemia injury on internal pyramidal layer of the parietal area from animals treated with L-Ala-Gln." (PMID 32696813, 2020). "One study showed that inhibiting the effects of IL-6 protein with systemic infusions of neutralizing antibodies attenuates ischemia-related increases in blood-brain barrier permeability by inhibiting IL-6, and modulates tight junction proteins after ischemia." (PMID 32194375, 2020). "HLJDT was proven to reduce the production of proinflammatory factors including IL-1β, TNF-α, IL-6, as well as IL-17, thus it is of great significance in alleviating ischemia." (PMID 33613277, 2020). "Ginsenoside Rb1 can reduce the release of TNF-α and IL-6 in a rat model of bone pain caused by cancer and it can inhibit the expression of TNF-α and IL-6 induced by intestinal ischemia/reperfusion injury in rats." (PMID 32020864, 2020). "IL-6 increases vascular endothelial cell monolayer permeability in vitro, and contributes to ischemia-related blood-brain barrier dysfunction." (PMID 32194375, 2020). "It is demonstrated that the increase of some cytokines including IL-6, IL-1β, and TNF-α in ischemia models are associated with pathways that participate in apoptotic neuronal death." (PMID 32963745, 2020). "Application of HYP9 in vivo alleviated the brain infarct lesion, astrocytes population, apoptosis, and interleukin-6 (IL-6) and IL-1β release in mouse cortices after ischemia." (PMID 33604333, 2020). "A growing body of evidences also suggests that MEK/ERK pathways are responsible for the elevated level of TNF-α, IL-1β, IL-6, and iNOS following ischemia, which further highlights their neuroinflammatory role." (PMID 31049133, 2019). "The most important inflammation related cytokines in brain during ischemia injury were IL-1, IL-6, COX-2, and TNF-α." (PMID 30854014, 2019).
ischemia (continued). "Gene expression of inflammatory mediators, monocyte chemoattractant protein 1 (MCP1), tumor necrosis factor (TNF)-α and interleukin (IL)-6, by real-time PCR also showed an ischemia time-dependent increase in the ischemic kidneys at the early stage of AKI." (PMID 30873045, 2019). "Our results show that TNF-α, IL-6, and IL-1 are increased in the left ventricle undergoing ischemia for 14 days, thereby increasing the damage." (PMID 30642049, 2019). "Astrocytes activated by ischemia and anoxia secrete many pro- and anti-inflammatory factors, such as IL-1β, IL-6, TNF-α, TGF-β, VEGF-A, MCP-1 CXCL-1, MMP-2, and MMP-9, which influence BBB integrity." (PMID 31779652, 2019). "The anti-IL-6 mAb infusions also diminished the ischemia-related increases in BBB permeability 24 h after ischemic injury, modifying tight junction and plasmalemma vesicle protein expression in the fetal brain." (PMID 29875342, 2018). "A study showed that after leukocytes infiltrated the injured kidney in a model of ischemia–reperfusion injury, they produced maladaptive IL-6 when their TLR4 receptors interacted with HMGB1 released by injured renal cells." (PMID 30197987, 2018). "We have previously shown that allograft-resident DCs increase IL-6 production in the setting of ischemia, and blockade of IL-6 improves allograft outcomes." (PMID 29410442, 2018). "Previous studies have shown that COX inhibitors are able to suppress TNF-α, IL-6, and IL-1β in renal tissue after ischemia." (PMID 29535870, 2018). "The neuroprotective effect of IL-6 is exemplified by its ability to protect cerebral granular neurons from N-methyl-D-aspartate-induced excitotoxicity in vitro and the fact that IL-6 injections into the brain after ischemia reduce ischemic brain injury." (PMID 30089504, 2018). "On the other hand, it was demonstrated that IL-6 has a neuroprotective action against ischemia and glutamate excitotoxicity and inhibits the spread of excitation, inhibiting the depolarization-evoked glutamate release from neocortical synaptosomes." (PMID 29921762, 2018). "IgG leakage, tight junction protein loss, and inflammatory cytokines IL-1β, IL-6, and TNF-α reduced in mesenchymal stem cell-treated mice compared to the control group following ischemia (p < 0.05)." (PMID 29724240, 2018). "The IL-6 level remains elevated starting at 4 h to 2 weeks post ischemia with the peak at 24 h post ischemia." (PMID 28115020, 2017). "At day 14 post‐ischemia, the levels of IL‐6 and TNF‐α in the exercise‐treatment group remained significantly lower than ischemia group." (PMID 29201553, 2017). "TNF-α, with its accomplice IL-6, induces the thrombin or even microthrombus formation on intestinal mucosa, leading to microcirculation disorder, grievous ischemia, and anoxia." (PMID 29156761, 2017). "Administration of SQ29548 inhibited microglia/macrophages activation and enrichment, including both M1 and M2 phenotypes, and attenuated ischemia-induced IL-1ß, IL-6, and TNF-α up-regulation and iNOS release." (PMID 27775054, 2016). "Compared with the ischemia group, the IL-1β and IL-6 serum levels were significantly reduced in the ischemia + low-, medium- and high-dose NaHS groups; in the ischemia + medium- and high-dose NaHS groups the TNF-α level in the serum was significantly reduced." (PMID 25667680, 2015). "Compared with the sham surgery group, the TNF-α, IL-1β and IL-6 serum levels in the rats were significantly elevated in the ischemia group (P<0.01)." (PMID 25667680, 2015). "Remarkably, it has been documented that IL-6 also has an anti-apoptotic function after focal ischemia." (PMID 26690124, 2015). "The induction of cerebral ischemia increased IL-6 mRNA expression levels significantly at 4 and 24 h following ischemia in the left ischemic hemispheres in the hypoxia group compared with those in the control group (P=0.002 for 4 and 24 h)." (PMID 24520277, 2014).
ischemia (continued). "In the present study, we demonstrated that the ischemia-induced up-regulation of iNOS, IL-1β, IL-6 and TNF-α was inhibited by treatment with GL." (PMID 24594628, 2014). "The higher IL-6 concentration in venous blood after DHCA is presumably a direct effect of ischemia on the endothelium and the intra- and perivascular leukocytes." (PMID 23390999, 2013). "Cytokines such as interleukin-6 (IL-6) are important mediators of inflammatory response in ischemia." (PMID 23557242, 2013). "IL-6 not only is found after ischemia of the brain, gut, and heart, but the amount of IL-6 also correlates with the amount of ischemic injury." (PMID 22290302, 2012). "IL-6 as a pleiotropic mediator can potentially exert detrimental (early phase) or beneficial effects (late phase) following ischemia." (PMID 22028848, 2011). "Various stimuli, such as infection, traumatic brain injury, ischemia and CNS diseases produce key inflammatory mediators including IL-6." (PMID 20205746, 2010). "Development of ischemia was demonstrated by changes in the CSF concentration of interleukin 6 (IL-6), tumor necrosis factor alpha (TNFa) and lactate, which are considered to increase when CNS ischemia ensues." (PMID 20230612, 2010). "Other researchers reported high local expression of IL-6 following ischemia in organs such as heart or brain, and in a rat model of ocular and brain ischemia." (PMID 19421412, 2009). "Iron overload following ischemia may be mediated through two primary pathways: IL-6–JAK/STAT3–hepcidin axis: Ischemia-induced IL-6 activates the JAK/STAT3 signaling pathway, which enhances hepcidin expression." (PMID 41425599, 2025). "Furthermore, we found that IL-6 expression was higher 3- and 5-day post-ischemia in the hippocampus of AhR+/+ mice compared with AhR-/- mice (*p = 0.0377; **p = 0.0091), supporting the role of AhR in exacerbating the neuroinflammatory response to ischemia." (PMID 41452851, 2025). "In patients with GCA, this possible compensatory mechanism through IL‐6‐induced angiogenesis may help to lessen ischemia episodes." (PMID 39817601, 2025). "We hypothesize that IgM may activate Fc receptors on mesangial cells, inducing pro-inflammatory cytokine release (e.g., IL-6) that could exacerbate arteriolosclerosis-induced ischemia." (PMID 40470049, 2025). "IGF decreases due to unknown reasons in ischemia, which usually positively correlates with factors such as IL-6 in this pathway." (PMID 39166055, 2024). "The expression levels of inflammatory factors IL‐1β, TNF‐α, and IL‐6 were simultaneously increased in both the ipsilateral L Core and L Edge at 3 days post‐ischemia, whereas the levels of these factors in the L Cortex region were similar to the contralateral side." (PMID 39252446, 2024). "It is also important to note that anti-IL-6 is found during in-vivo ischemia, suggesting that IL-6 may be responsible for the increased permeability of the blood-brain barrier after injury." (PMID 38425701, 2024). "Interestingly, we observed strong release of ATP immediately after the release of ischemia, reaching mid-micromolar concentrations in the extracellular space, which is known to stimulate IL-6 formation." (PMID 36943408, 2023). "In addition, intravenous administration of hUC-MSCs effectively downregulated the expression of pro-inflammatory cytokines, including IL-1β, TNF-α, matrix metalloproteinase 9, and IL-6, which are upregulated by ischemia." (PMID 36829224, 2023). "Cytokines such as IL-1-β and IL-6 from blood vessel endothelial cells and phagocytic mononuclear cells are rapidly synthesized and released into circulation during ischemia and IR, along with increased oxidative stress and inflammation during IR blood flow deceleration and oxygen restriction." (PMID 37132757, 2023).
ischemia (continued). "We next explored whether adenosine mainly produced by cardiomyocytes during an acute ischemic event and released into the coronary circulation immediately after the release of ischemia can alter the initial production of IL-6 by the heart." (PMID 36943408, 2023). "In addition to endogenous toxins, inflammatory factors, including IL-1 and IL-6, produced during ischemia enter the circulatory system." (PMID 35642042, 2022). "We found it interesting that there is a time–effect relationship among the IL-6 increasing levels, and intervention at a certain time period may alleviate ischemia in ischemia–reperfusion injury." (PMID 36091399, 2022). "The upregulation of let-7a-5p in microglia has been found to correlate with protection from ischemia and neuroinflammation by inhibiting the expression of pro-inflammatory factors (e.g., IL-6, iNOS) and boosting the expression of anti-inflammatory factors (IL-10 and IL-4)." (PMID 35682695, 2022). "In the present study, we analyzed the levels of TNF-α, IL-1β, and IL-6 in the hippocampus to validate the roles of Tat-SH3GL2 on ischemia-induced inflammatory responses because TNF-α promotes the migration of neurotrophils, IL-1β, and IL-6, which show pro-inflammatory roles." (PMID 33572372, 2021). "Neither did we find any evidence that exercise-induced ischemia per se was linked to an exaggerated IL-6 response." (PMID 33288784, 2020). "Reperfusion injury after ischemia is characterized by a severe immune response, including elevated reactive oxygen species and an increase in pro-inflammatory cytokines, including IL-1β, IL-6 and TNF-α." (PMID 31513644, 2019). "After cerebral ischemia, IL-6 levels increase and peak around 3 days after ischemia." (PMID 30245755, 2018). "Therefore, inhibiting the effects of the IL-6 protein with systemic infusions of neutralizing antibodies attenuated ischemia-related increases in BBB permeability by inhibiting IL-6 after ischemia." (PMID 29875342, 2018). "In addition to MCP-1, IL-6 mRNA expression in the saline-pretreated group also increased significantly after ischemia and this elevation persisted along with a significant increase in the neutrophil chemoattractant, KC (CXCL1) seen at 24 h reperfusion." (PMID 28182087, 2017). "The etiologic role of released IL-6 in stimulation of myocyte ICAM-1 was previously demonstrated by others, and binding of neutrophils to ICAM-1 is considered to be a causal factor in myocyte injury after ischemia." (PMID 26935770, 2016). "Also IL-6 as a pleiotropic mediator can potentially exert detrimental or beneficial effects following ischemia, as the administration of antimouse IL-6 receptor monoclonal antibody or knocking out IL-6 gene increased infarct size." (PMID 23533818, 2013). "IL-6 expression is increased in the brain following ischemia, and damaged neurons may contribute to increased IL-6 levels." (PMID 23497639, 2013). "It appears that lower IL-6 levels may induce a deregulation leading to an exacerbated inflammation, a poor angiogenesis and fetal death by ischemia." (PMID 22269218, 2012). "For instance, hypoxic cardiomyocytes produce interleukin-6 (IL-6) which could contribute to the myocardial dysfunction observed in ischemia reperfusion injury." (PMID 18472818, 1997). "Interestingly, a combined application of FGF-2 and VEGF increased tube formation of endothelial cells as compared to both factors alone, and a combination of MSC-derived VEGF, MCP-1, and IL-6 was identified as a driving mediator of angiogenesis in a hindlimb ischemia model." (PMID 37626914, 2023). "However, the concentration of three cytokines, KC/GRO (CXCL1), IL-6, and TNFα, were showed to be significantly increased in the coronary effluents of the hearts after IR injury (after ischemia and 60 min of reperfusion) compared with the basal conditions (collected at 10 min stabilization, basal)." (PMID 34616778, 2021).